MAGEA3 (MAGE family member A3)
Diseases named in the same sentence as MAGEA3 in open-access papers (continued):
Sharing a sentence is not in itself a finding about the gene and the disease.
tumor (continued). "There were 10 lncRNAs that were expressed in more than 20% of the tumor samples (LINC01980, AC025254.1, LINC02806, LINC02476, LINC02506, AL162413.1, LINC00221, LINC01287, AC079466.1, and LINC01419), compared to five protein-coding genes (MAGEA1, MAGEA3, SSX1, DCAF4L2, and MAGEC2)." (PMID 38985879, 2024). "The poor clinical outcome could also be due to the use of tumor antigens overexpressed or present in other tissues (NY-ESO-1, MUC1, MAGEA3, MART1, HER2) and the persistence of an immunosuppressive environment that would prevent the activity of DCs once entering the TME." (PMID 37190135, 2023). "In addition, it was shown that MAGEA3-IgG Fc fusion proteins failed to bind to PD-L1+ tumor cells, further ruling out the non-specific binding of IgG Fc domain to tumor cells." (PMID 32170083, 2020). "We also examined the differences in MAGEA3 and MAGEA6 expression between tumor tissues and adjacent normal tissues." (PMID 41452900, 2025). "Due to lack of commercially available murine MAGEA2, MAGEA3 or MAGEA10 antibodies, DT6066 and TB32048 (spontaneous KPC tumor derived cells) cells were chronically exposed to Gem until they became resistant." (PMID 37814317, 2023). "MAGEA3 and CXorf61 expression was found in 3/23 (13%) of the DCIS samples but neither gene was detected in LCIS or benign lesions." (PMID 25593980, 2014). "This may explain why MAGEA3 and VEGF, despite their negative regulatory relationship in tumor cells, do not fully correlate and have different prognostic effects in CRC populations." (PMID 40342736, 2025). "Our clinical studies have revealed that the expression of MAGEA, particularly MAGEA2, MAGEA3, and MAGEA10, but not other family members, may play a crucial role in determining tumor growth, chemoresistance, and cancer progression in multiple cancers." (PMID 37814317, 2023). "Noticeably, overexpressed NYESO1 (CTAGB1), MUC1, MAGEA3, MAGEA4, or CEA (CEACAM5) antigens did not correlate with TERT improved PFS of patients with high B cell infiltrate, suggesting a selective role of TERT over other common tumor antigens in driving local antitumor immunity." (PMID 36909826, 2023).
cancer (210 papers, 2001 to 2025). A tumor composed of atypical neoplastic, often pleomorphic cells that invade other tissues. "Melanoma-associated antigen 3 (MAGEA3) is a member of the class I melanoma antigen (MAGE) family proteins belonging to the cancer-testis antigens." (PMID 40342736, 2025). "Melanoma-associated antigen-A3 (MAGEA3), a prominent member of cancer testis antigen, is as a potential immunotherapeutic target due to its elevated expression in various malignant tumor cells." (PMID 38229155, 2024). "MAGEA3 are antigens encoded by cancer-germline genes, and have been identified as a potential prognostic biomarker and pro-survival factor in multiple types of cancer." (PMID 38555374, 2024). "One of the most frequently reported germ cell genes across various cancer types (including PCA) is melanoma associated antigen A3 (MAGEA3)." (PMID 31287009, 2019). "The expression of MAGEA3 stimulates cell cycle progression and rate of migration and invasion in thyroid cells in vitro; these characteristics are associated with aggressive behavior in cancer cells." (PMID 28415749, 2017). "Since VEGF is a major angiogenic factor produced by cancer cells and also the target of bevacizumab, we first investigated the impact of MAGEA3 on VEGF in cancer cells." (PMID 40342736, 2025). "On the other hand, TFPI-2 was found to be up-regulated when melanoma-associated antigen 3 (MAGEA3) was silenced leading to impaired VM, with the implication that the influence of TFPI-2 on VM in different cancers requires further investigation." (PMID 39153052, 2024). "As demonstrated by others, we found using Pearson correlation test that SS and MRCL highly express cancer–testis (CT) antigens, specifically MAGEA3/A6 and MAGEA12." (PMID 35267598, 2022). "Sometimes cancer patients with MAGEA3 mRNA positive still manifest MAGEA3 immunotherapy resistance because no functional protein was produced at all." (PMID 34970496, 2021). "Next, we examined the expression of MAGEA12 and MAGEA3 in normal tissues and various cancer cell lines by using genotype-tissue expression (GTEx) and Cancer Cell Line Encyclopedia (CCLE), respectively." (PMID 34202157, 2021). "The characteristics of differential expression in normal and cancer tissues make MAGEA3 an ideal target for antitumor vaccines and carried out various clinical trials." (PMID 34970496, 2021). "Melanoma-associated antigen-A3 (MAGEA3), one of the members of the cancer-testis antigen (CTA) family, was considered an important part of cancer immunotherapy." (PMID 34970496, 2021). "For a long time, MAGEA3 has been on light for hope as cancer immunotherapeutic; however, recent findings emphasizes on its functional role in the pathogenesis of different malignancies." (PMID 31287009, 2019). "Previously, constitutive overexpression of MAGEA3 in different cancer cell lines has been used to investigate its functional role." (PMID 31287009, 2019). "In our present study, we observed MAGEA3 as a survival factor for the cancer cells during GF-deprived stress condition." (PMID 31287009, 2019). "Further, we were interested in evaluating the contribution of MAGEA3 towards cancer cells survival during genotoxic and metabolic stress by using existing therapeutic molecules and metabolic switch modulators." (PMID 31287009, 2019). "In the past, various studies have shed importance on the functional characterization of the cancer-specific gene MAGEA3; however, its functional role in PCA is yet to be elucidated." (PMID 31287009, 2019). "MAGEA3/6 expression has shown to drive several hallmarks of cancer such as cell proliferation, cell migration, invasion and anchorage-independent growth and are also sufficient to drive tumorigenic properties of non-cancerous cells." (PMID 31217903, 2019). "A recent study reported that a cancer‐specific ubiquitin ligase, MAGEA3/6‐TRIM28, participates in AMPK‐α1 degradation leading to inhibition of autophagy in HeLa, HEK‐293, and U2OS cells." (PMID 29094484, 2017).
cancer (continued). "In one clinical trial, 9 cancer patients received engineered T-cells targeting a peptide-HLA complex involving peptide KVAELVHFL from MAGEA3 and HLA-A*02:01." (PMID 27439771, 2016). "We decided to also include MAGEA3 in this analysis as it is the CT gene that is currently in the most advanced stage in clinical trials of therapeutic CT-based cancer vaccines." (PMID 25593980, 2014). "An additional study has previously shown that NY-ESO-1 and MAGEA3 are upregulated in a proportion of patients treated with 5-aza-2′-deoxycytidine in cancers involving the lung, esophagus, or pleura." (PMID 19997593, 2009). "Furthermore, we discovered that MAGEA3 significantly impairs mitochondrial function in cancer cells, suggesting an additional layer of complexity in its oncogenic role." (PMID 40342736, 2025). "MAGEA3 cancer vaccine has entered several clinical trials for cancer treatment." (PMID 37814317, 2023). "The mRNA expression of MAGEA3 in pan-cancer was first analyzed on the TIMER website." (PMID 34970496, 2021). "MAGEA3 (MAGE family member A3)/MAGEA6 are frequently reactivated in cancer cells and bind to the TRIM28 E3 ligase, which ubiquitinates PRKAA1/AMPKα1 (protein kinase AMP-activated catalytic subunit alpha 1), promoting the degradation of AMPK and the inhibition of autophagy." (PMID 32887506, 2020). "In the current study, we report the cancer-promoting/favoring role of MAGEA3 in PCA." (PMID 31287009, 2019). "Previous studies have shown the role of MAGEA3 in cancer cells metabolism." (PMID 31287009, 2019). "On the contrary, intra-molecular diversification of the T-cell response reported for self-antigens such as MAGE Family Member A3 (MAGEA3) or Telomerase (TERT) provided stronger evidence that a true break of immune tolerance occurred in the few patients successfully reacting to cancer vaccines." (PMID 38571942, 2024). "In addition to the KRAS and SALL4oncogenes, CGS4 tumors highly express cancer-testis antigens (CTAs) such as MAGEA3 and MAGEA12, indicating that they might be good candidates for testing CTA-mediated cancer vaccine therapy." (PMID 37674200, 2023). "Vaccines against MAGEA3, NY-ESO-1 and PRAME can elicit cancer-specific T cell responses implying potentially increased immunogenicity of HNSCC in response to DAC treatment." (PMID 39608124, 2025). "Computational analysis initially identified 40 cancer-active CTA genes, of which four genes (LY6K, MAGEA3, CEP55, and ATAD2) were most indicative of nodal spread." (PMID 41009820, 2025). "Among the most significant genes, a decrease in keratins in HGSIL compared with LGSIL stands out as well as the overexpression of members of the MAGE gene family of cancer/testis antigens in ASCC compared with HGSIL, like MAGEA4, MAGEA3, and MAGEA1." (PMID 39024554, 2024). "MAGEA2, MAGEA3, MAGEA4, MAGEA6, and MEGEA12, members of the MAGE family, have been studied for their potential for cancer immunotherapy." (PMID 37655157, 2023). "To further validate the clinical significance of our findings, we conducted a pan-MAGEA analysis using the KM plotter and TIMER2.0 databases, which includes data from various cancers, summing the expression of MAGEA2, MAGEA3, and MAGEA10." (PMID 37814317, 2023). "The relationship between MAGE-A proteins and ubiquitination is well known; for example, MAGEA3 and MAGEA6 form an E3 ubiquitin ligase complex with TRIM28, which participates in the survival of cancer cells by degrading AMPKa1." (PMID 34202157, 2021). "The data shows cell line dependent expression pattern of MAGEA3 in PCA, and further supports the known sporadic nature of its expression in different other cancers." (PMID 31287009, 2019). "Examples of biclusters from this category include the biclusters consisting of genes from the Cancer-Testis antigens family—MAGEA2, MAGEA3, MAGEA6, MAGEA10, CSAG1, CSAG2, CSAG3 (Xq28)/CT45A3, CT45A5, CT45A6 (Xq26.3)." (PMID 31216036, 2019).
cancer (continued). "Notable exclusions include the cancer/testis antigens MAGEA1, MAGEA3, MAGEA6, GAGE1, GAGE2, GAGE4 and GAGE5, which were originally identified as being strongly upregulated in the PR subgroup but are not upregulated in our PTTG1 high patients." (PMID 26445238, 2015). "We then found that high expression of MAGEA3 reduces VEGF expression and secretion in cancer cells." (PMID 40342736, 2025). "MAGEA3, a cancer-testis antigen, is present in various cancers, the testis, and the placenta, but absent in other somatic cells." (PMID 38720887, 2024). "Interestingly, known CTAs, such as MAGEA3, MAGEA1, DSCR8, MAGEC2, and MAGEA6, tended to be identified in the largest number of cancer types." (PMID 39561714, 2024). "Moreover, our analysis revealed cell-specific expressions, such as CARD11 in cancer cells, PNMA2 in proliferative cells, MAGEA3 in gland mucous cells, and KIT in chief cells." (PMID 38962317, 2024). "Analogously to the oncogenic potential of MAGEA3/A6 expression in tumors resulting in enhanced proliferation by limiting mTOR-dependent autophagy, a similar role of MAGED2 is conceivable, which is abundantly expressed in many types of cancers." (PMID 37686237, 2023). "Also, together with MAGEA3/6, TRIM28 forms a cancer-specific ubiquitinase that targets AMPK—the “metabolic switch” in cancer, for proteasomal degradation." (PMID 36674511, 2023). "LINC01234 is considered to be related to the drug resistance of cancer patients, and a study displayed that LINC01234 can increase the resistance of cancer cells to chemotherapeutic drugs by regulating the LINC01234/miR-31-5p/MAGEA3 axis." (PMID 33585468, 2020). "Virtually no attention is given to the likelihood of toxic cross-reactivity which has led to the focus on MAGEA3 and other cancer-testes antigen genes that are not expressed in essential, normal human tissues." (PMID 27439771, 2016). "Genes such as MAGEA3 and MAGEA6 contributed targets for 7 cancer types each, while genes such as UMODL1, NLRP4, MAGEC2, ANKRD30A, and GPRC6A contributed targets for only 1 cancer type." (PMID 27439771, 2016). "However the cells, those are negative for MAGEA3 expression, don’t depend on it when desired growth factors are available, but in growth factor limiting condition, ectopic expression of MAGEA3 is able to help the cancer cells to survive." (PMID 31287009, 2019). "In our study, results showed that MAGEA3 did not upregulate the expression of PDGF, FGF, and ANGPT2 but could lower glycolysis and respiration levels in cancer cells." (PMID 40342736, 2025). "Indeed, transcripts for a number of antigens such as CTAG2, MAGEA3, and MAGEA6, which are normally expressed in testis and are immunogenic when aberrantly expressed in cancer tissue, were strongly expressed in a subset of IE1, but not IE2, samples." (PMID 36609566, 2023). "Similarly, expression of MAGEA3, MAGEA6 and MAGEA12 was greater than 3-fold in all cancer lines, regardless of origin, when compared to HEK cells." (PMID 32760472, 2020).
lung (1 paper, 2024). "Brother of the regulator of imprinted Sites (BORIS) was reported that it bound to the promoters of MAGEA3 genes and was associated with their transcriptional activation in lung cancer." (PMID 38555374, 2024).
MAGEA3 also shares sentences with these, for which no sentence is quoted: multiple myeloma (15 papers); esophageal squamous cell carcinoma (6); esophageal cancer (5); glioma (5); adenocarcinoma (4); myxofibrosarcoma (4); neuroblastoma (4); undifferentiated pleomorphic sarcoma (4); acute myeloid leukemia (3); astrocytomas (3); breast tumors (3); lung squamous cell carcinoma (3); cancer testis (2); colon adenocarcinoma (2); head and neck squamous cell carcinoma (2); malignant peripheral nerve sheath tumor (2); metastatic disease (2); oral squamous cell carcinoma (2); seminoma (2); adenoma (1); atrial tachycardia (1); Autoimmunity (1); basal cell carcinoma (1); benign tumors (1); brain tumour (1); chondrosarcoma (1); chronic myeloid leukemia (1); colitis (1); colorectal tumors (1); endometrial carcinoma (1).
A further 38 diseases each share a sentence with MAGEA3 in 1 paper.